EPO (erythropoietin)
Diseases named in the same sentence as EPO in open-access papers (continued):
Sharing a sentence is not in itself a finding about the gene and the disease.
chronic kidney disease (continued). "Most importantly, novel inhibitors of PHDs, specifically PHD2 inhibitors, markedly intensify the nuclear expression of HIF-2α in EPO-producing peritubular cells located in the deep cortex, and are now approved for use as EPO inducers in patients with advanced chronic kidney disease." (PMID 37510986, 2023). "Notably, however, in chronic kidney disease, when EPO production is restricted due to kidney damage, haemoglobin levels are higher for higher BMI and lower EPO doses are required to maintain haemoglobin levels in obese compared to normal weight patients." (PMID 37528422, 2023). "Importantly, studies have shown that MT can promote EPO sensitivity in anemic patients with chronic kidney disease or chronic renal failure." (PMID 37624196, 2023). "A minor improvement in Hb and platelets could perhaps be due to the addition of iron and erythropoietin therapy in patients with chronic kidney disease." (PMID 36827665, 2023). "This ensures that the chronic renal insufficiency effects on the body such as hypertension, hypercalcemia, low vitamin D levels, the need for erythropoietin stimulating agents, and the preservation of renal function are monitored and align with other chronic kidney disease populations." (PMID 37232792, 2023). "Conversely, chronic kidney diseases (CKDs) lead to diminished EPO production and anemia." (PMID 37494095, 2023). "Reduced red blood cells (RBC) survival, common in chronic kidney disease (CKD) even in early stages by impairment of erythropoietin production, may also affect HbA1c values." (PMID 35951657, 2022). "The lack of erythropoietin and the imbalance of iron metabolism are currently recognized causes of anemia in patients with chronic kidney disease." (PMID 36420092, 2022). "Further, patients with chronic kidney disease may have a lower hemoglobin because of erythropoietin deficit, especially right after transplant." (PMID 35449717, 2022). "Similarly, administration of EPO to patients with chronic kidney disease improved vaccine responsiveness." (PMID 35746541, 2022). "Anemia is one of the most common consequences of advanced chronic kidney disease and end-stage renal disease (ESRD), because renal disease leads to a relative deficiency of EPO that contributes to fatigue, reduced exercise tolerance, and negatively impacts patient quality of life." (PMID 34326344, 2021). "If implanted as an arteriovenous vascular graft, such a construct could serve a dual role as an EPO delivery platform and hemodialysis access for patients with end-stage renal disease." (PMID 34326344, 2021). "However, the increase in plasma EPO concentration in patients with end-stage renal disease treated with the full therapeutic success of HIF-PHI is significantly lower than in patients treated with recombinant human erythropoietin [rhEPO] injections." (PMID 33567688, 2021). "EPO stimulated FGF23 production in mouse and human, increasing serum FGF23 and reducing serum phosphate, and may contribute to elevated FGF23 in chronic kidney disease patients receiving EPO." (PMID 33330462, 2020). "Renal anemia in chronic kidney disease is treated with recombinant human erythropoietin (rhEPO)." (PMID 31977161, 2020). "Following the successful cloning of the EPO gene in 1985, human recombinant erythropoietin (rHuEPO) was developed and has been available in Japan for dialysis patients since 1990 and for patients with chronic renal failure since 1994, providing outstanding outcomes." (PMID 32998272, 2020). "In addition, immunomodulatory agents for in vivo iTreg generation can be considered such as hormone erythropoietin, as its application to patients with chronic kidney disease resulted in an increase of Tregs after 6 months of treatment." (PMID 32300340, 2020). "Moreover, the Siwu plus EPO group improved the level of oxidative stress in rats with chronic renal failure and reduced the expression of inflammatory factors." (PMID 31915448, 2019).
chronic kidney disease (continued). "The decreased reticulocyte count in older patients with SCD may also have reflected reduced erythropoietin levels in the context of the onset of chronic kidney disease, as evidenced by the higher creatinine in the older age group." (PMID 30459954, 2018). "Indoxyl sulfate may also inhibit erythropoietin expression in animal models with chronic kidney disease." (PMID 29137321, 2017). "Lower value may also be encountered due to chronic kidney disease that results in decreased erythropoietin production and decrease capacity of bone marrow to produce RBC, which ultimately results in lower TEC production." (PMID 27047084, 2015). "Similarly, short-term continuous subcutaneous human GH administration (rhGH 2 μg/kg body weight per 0.1 mL/h for 72 h) in anemic patients with chronic renal failure was able to ameliorate plasma EPO levels and reticulocyte counts." (PMID 26779261, 2015). "On the other hand, EPO effects seem to be context-dependent, as EPO produced in brain, liver, spleen, lung and testis (where EPO mRNA was detected) is unable to substitute for renal EPO in chronic kidney disease, and brain EPO seems to act locally as neuroprotector." (PMID 24592241, 2014). "Effects of aging such as increased levels of inflammatory mediators and diminished capacity to secrete erythropoietin may mimic chronic kidney disease." (PMID 24709756, 2014). "The role EPO plays in iron-deficiency-related thrombocytosis has garnered much interest, as administration of human recombinant EPO (rh-EPO) results in thrombocytosis of varying degree and duration in healthy controls as well as patients with chronic kidney disease." (PMID 22084665, 2011). "Hyporesponsiveness to therapeutic erythropoietin has emerged as an important consequence of inflammation, especially in chronic kidney diseases, and may be a consequence of iron restriction imposed by high hepcidin." (PMID 20066043, 2010). "Other trials with EPO administration to diabetic, chronic renal diseased patients have shown that EPO significantly improves several metabolic parameters including fasting glucose level and insulin sensitivity as measured by euglycaemic hyperinsulinaemic clamp and intravenous glucose tolerance test." (PMID 19521513, 2009). "However, anemic patients with renal chronic failure need continuous EPO for their red cell synthesis." (PMID 15910687, 2005). "In individuals with advanced chronic kidney disease (CKD), especially those on dialysis, there is a marked decline in both EPO production and renal mass." (PMID 41012526, 2025). "Although data in humans are limited, some studies in patients with chronic kidney disease (CKD) receiving recombinant human EPO have reported improved metabolic markers, suggesting potential translational relevance." (PMID 41012526, 2025). "However, SFGC label indication is for patients 6 years and older with chronic kidney disease undergoing hemodialysis in conjunction with supplemental erythropoietin therapy, so further data investigating its use in the hospitalized child are limited and retrospective." (PMID 40003291, 2025). "The molecular mechanisms associating chronic inflammation with anisocytosis have been hypothesized among diabetic and chronic kidney disease patients including a decrease in erythrocyte lifespan, suppression in erythropoietin response, and impairment in iron metabolism." (PMID 38923843, 2024). "In chronic kidney disease (CKD), renal mesenchymal fibroblasts are converted to myofibroblasts, losing their ability to produce EPO but participating in renal fibrosis, leading to renal anemia." (PMID 39670089, 2024). "For her normocytic anemia, which was due to chronic kidney disease (CKD) of cardiovascular origin, she received erythropoietin." (PMID 36534207, 2023). "Patients with chronic kidney disease (CKD) develop renal anemia and exhibit reduced erythropoietin secretion." (PMID 36432138, 2022).
chronic kidney disease (continued). "Anaemia is a common manifestation of chronic kidney disease (CKD) because of the reduced production of erythropoietin by the diseased kidneys." (PMID 35565102, 2022). "However, though both epoetins alpha and beta demonstrated comparable efficacy and safety profiles, epoetin beta achieved targeted hematocrit levels with lower doses and kept the occurrence of hemoglobin levels above 13 g/dL in EPO-treated end-stage renal disease hemodialysis patients." (PMID 34281163, 2021). "These activities demonstrated in animal models suggest that, while some non-hematopoietic EPO responses may be protective, bone health may be adversely affected with chronic EPO treatment such as that associated with chronic kidney disease." (PMID 33330462, 2020). "Previous studies have reported that several factors, including iron deficiency, vitamin deficiency, chronic kidney disease-mineral and bone disorder (CKD-MBD), inflammation, and malnutrition are associated with erythropoietin resistance." (PMID 32003308, 2020). "In addition, administration of exogenous EPO may increase the risk of cardiovascular events in patients with chronic kidney disease (CKD) and end stage renal disease (ESRD)." (PMID 32512806, 2020). "Interestingly, patients with chronic kidney disease who require high‐dose erythropoietin were found to have higher levels of circulating pro‐inflammatory biomarkers IL6 and CRP that may translate to higher levels of VTE." (PMID 35847693, 2020). "Anemia is a hallmark of chronic kidney disease (CKD), and erythropoietin (EPO) deficiency and reduced iron bioavailability by high hepcidin levels are fundamental factors underlying this condition in CKD." (PMID 30995819, 2019). "Due to important alterations in phosphate balance in chronic kidney disease (CKD), most research on FGF23 up until now was focused on CKD (see section “EPO, Iron, CKD, and Inflammation Are Important Regulators of iFGF23 Cleavage”)." (PMID 30971944, 2019). "Renal anemia is a major complication of chronic kidney disease (CKD), predominantly due to the failure of the kidneys to produce sufficient endogenous erythropoietin to stimulate the bone marrow to produce red blood cells (RBC)." (PMID 29168688, 2018). "In chronic kidney disease (CKD), recombinant erythropoietin (rhEpo) can be administrated to increase RBCV and thereby correct [Hb] toward “normal” values." (PMID 30426716, 2018). "Although rHu-EPO increases blood pressure in patients with chronic renal failure and cancer, the mild event observed in one subject could be considered an isolated event within the framework of the study, considering that the rest of subjects preserved normal values." (PMID 28676085, 2017). "We studied the influence of EPO on MVs derived from MSCs, and the protective effects of these factors in subjects with chronic kidney disease (CKD)." (PMID 25998259, 2015). "Furthermore, EPO retards the progression of atherosclerosis in chronic kidney disease patients." (PMID 26101463, 2015). "As with patient studies of EPO administration in chronic kidney disease and stroke, comorbidities and concomitant treatments such as a clot-busting (thrombolytic) drug for reperfusion therapy are also likely to influence responses to EPO treatment in myocardial infarction." (PMID 24918289, 2014). "It exerts anti-inflammatory and anti-fibrotic effects, promotes autophagic clearance, and induces erythropoietin (EPO) production in the diabetic kidney, especially when the activation begins at the late stage of chronic kidney disease." (PMID 39648258, 2025). "It has been observed that treating chronic kidney disease (CKD) patients with EPO may lead to severe arterial HTN." (PMID 39011232, 2024). "The patient is now 17 months old on home CCPD, on chronical kidney disease (CKD) medications including calcium-based phosphate binders, alphacalcidol, cholecalciferol, erythropoietin and folic acid." (PMID 37013475, 2023).
chronic kidney disease (continued). "Patients with chronic kidney disease (CKD) develop renal anemia and reduced erythropoietin secretion." (PMID 35318301, 2022). "Regarding end-stage renal disease (ESRD), parallel with kidney dysfunction, renal anemia primary manifests due to impaired erythropoietin (EPO) production by specialized peritubular cells." (PMID 35464768, 2022). "As kidney function declines in chronic kidney disease (CKD) progression, the erythropoietin production decreases, and it exacerbates anemic condition due to lowering of iron level." (PMID 35239732, 2022). "The same group designed a long-term, prospective study on patients with chronic renal failure subjected to three therapeutic protocols: LPD plus KA plus erythropoietin (EPO), LPD plus EPO, and LPD alone." (PMID 33670711, 2021). "In diabetic patients with chronic kidney disease, SGLT2 inhibitors can also increase hemoglobin levels by promoting the production of EPO." (PMID 33776773, 2021). "The patient received oral allopurinol daily and treatment for end-stage renal disease (ESRD), which included regular dialysis and subcutaneous administration of erythropoietin." (PMID 31985336, 2020). "Erythropoietin is a major regulatory hormone of erythrocyte production that is produced from the kidney, and its levels are decreased in patients with chronic kidney disease (CKD)." (PMID 33331829, 2020). "Therefore, this study aimed to determine whether a biosimilar DA-α has similar efficacy and safety as that of EPO when given at a reduced dose frequency for the treatment of renal anemia in Indian patients with end-stage renal disease (ESRD) undergoing dialysis." (PMID 30866856, 2019). "However, it is not known whether supplementation with EPO reduces the risk of dementia in end-stage renal disease (ESRD) patients receiving hemodialysis (HD)." (PMID 31484803, 2019). "In patients with chronic renal disease, decreased low-grade inflammation was reflected by reduced WBC counts following EPO treatment." (PMID 29385149, 2018). "In chronic kidney disease (CKD) patients, as the degenerative and fibrosis process progresses, erythropoietin production is reduced and secondary anemia ensues." (PMID 26939055, 2016). "Erythropoietin (EPO) was first utilized for treating anemic patients of various etiologies, such as patients with end-stage renal disease on regular hemodialysis." (PMID 25888250, 2015). "Hyporesponsive to EPO therapy or EPO resistance and effectiveness of hepatitis B virus (HBV) vaccination in patients with end-stage renal disease (ESRD) are important issues among these patients." (PMID 24693515, 2013). "Recombinant human erythropoietin (rHuEPO) has been considered as a novel reno-protective therapy beyond the hematopoietic effect in AKI and chronic kidney disease (CKD)." (PMID 23829828, 2013). "EPO doses used in these studies are considerably higher, ranging from 3000–5000 U/kg, which is much higher than the dosages usually applied in CKD and end-stage renal disease patients." (PMID 22957013, 2012). "In our previous studies, 150 or 75 U/kg (3 times/week, s.c.)of EPO were injected in rat models of type 1 diabetes mellitus, hypertension, and chronic kidney disease, and these doses of EPO did not affect hematocrit levels." (PMID 40943240, 2025). "Despite having advanced chronic kidney disease, his ferritin (270 μg/L), iron saturation (37%), and hemoglobin (126 g/L) were reasonable at that time without the use of iron supplements or erythropoietin stimulating agents." (PMID 39290404, 2024). "Additionally, treatment using YGY extract significantly mitigated cognitive deficits in a chronic renal failure mice model by up-regulating the CaMKIIα/CREBBDNF and EPO/EPOR pathways in the hippocampus." (PMID 36875644, 2023). "We found that parathyroidectomy did not significantly affect hemoglobin levels in end-stage renal disease patients, possibly due to irreversible damage to the renal interstitium and a consequent decrease in erythropoietin production." (PMID 37568150, 2023).
chronic kidney disease (continued). "From the point of production origin of EPO view, kidney mostly, there are studies which reported chronic renal failure in COPD patients even with normal kidney-related functional serum markers (e.g., blood urea nitrogen and creatinine) following the impairment of EPO production." (PMID 37117600, 2023). "Ferumoxytol has been included into nanoparticles for the treatment of patients with chronic kidney disease or end-stage renal disease who do not produce enough erythropoietin." (PMID 35071609, 2022). "From the database, we identified 147,318 end-stage renal disease (ESRD) patients on hemodialysis who had been diagnosed in 2000–2014 to establish the propensity-score-matched EPO user cohort and non-EPO user cohort with equal sample size of 15,992." (PMID 36077032, 2022). "Key systems for the pathogenesis of pallor in chronic kidney disease include an overall lack of erythropoietin, iron inadequacy and malnutrition, expanded blood misfortune, and abbreviated erythrocyte life expectancy." (PMID 36060352, 2022). "rhEPO has been commercially available since 1989 after gaining authorization approval by the FDA (EPOGENR) for use as a valuable biologic medicinal product in the replacement protein therapy (RPT) of chronic renal failure (CRF), that is characterized by insufficient production of EPO." (PMID 34440909, 2021). "The baseline value of serum EPO at 8 weeks after 5/6Nx, a model of chronic kidney disease, without sepsis was higher than non-Nx mice despite the lower renal mass in 5/6Nx mice." (PMID 34831360, 2021). "Similar to patients with chronic kidney disease, EPO serum levels failed to increase in the anemic Foxd1Cre::Pdgfrb+/J mice." (PMID 31943786, 2020). "Administration of IV iron therapy without erythropoietin can improve Hb levels, even in patients with chronic kidney disease." (PMID 35236435, 2020). "We are not aware of studies in end-stage renal disease patients that quantify changes in erythroid precursor cell apoptosis rate or maturation velocity in response to erythropoietin levels." (PMID 29668766, 2018). "In chronic renal failure, erythropoietin treatment improved the anemic state with no change of iron status." (PMID 28739553, 2018). "In particular, IGF-1 seems to play an important role in the regulation of erythropoiesis in patients with end-stage renal disease and erythrocytosis without an increased EPO production." (PMID 26779261, 2015). "Moreover, in diabetic chronic kidney disease (CKD) patients endogenous EPO levels are positively correlated with markers of inflammation and are predictive of mortality, suggesting that the intrinsic EPO-EPOR system has essential functions in inflammation and infection control in vivo." (PMID 22094132, 2012). "Previously, we have reported that a low dose of EPO, which did not affect the hematocrit level, attenuated endothelial dysfunction and macrophage infiltration in aortas of diabetic, hypertensive, and subtotal nephrectomized chronic kidney disease rat models." (PMID 40943240, 2025). "In a 24-week, multicenter trial from 15 countries (n = 252 chronic kidney disease patients), daprodustat (an oral hypoxia-inducible factor-prolyl hydroxylase inhibitor) and controls (received recombinant human erythropoietin) did not markedly impact SBP and DBP." (PMID 37432331, 2023). "However, in end-stage renal disease and in nondialysis chronic kidney disease patients, treatment with EPO or ESA (erythropoiesis stimulating agents) showed inadequate efficacy and cardiovascular toxicity in terms of risk of cardiovascular hospitalization or stroke." (PMID 39502472, 2024). "Finally, in patients with chronic kidney disease (CKD) the positive effects of vitamin D on erythropoiesis could also be related to its suppressive effects on PTH, which directly inhibits erythroid progenitors, EPO synthesis, and red blood cells survival." (PMID 25781618, 2015).